INS (insulin)
Diseases named in the same sentence as INS in open-access papers (continued):
Sharing a sentence is not in itself a finding about the gene and the disease.
Obesity (continued). "However, no study thus far has evaluated whether obesity and sex determine central insulin effects on neural FCR." (PMID 35715625, 2022). "GLP-1 secretion is impaired in obesity and T2DM, and whether insulin resistance of the L-cell may explain impaired insulin secretion in these diseases is unclear; but, given the insulin-resistant state of pregnancy, it is possible that maternal L-cells may be less responsive to insulin in pregnancy." (PMID 35099411, 2022). "However, individuals without obesity had a lower, but significant, reduction in insulin sensitivity by 25.3% (baseline = 29.2 ± 18.4, post: 18.7 ± 14.2; p < 0.05) and significant differences were observed for absolute and percent changes in insulin sensitivity between groups (p < 0.05)." (PMID 35564376, 2022). "However, although the in vivo P4HA3 silencing by intraperitonealinjection with AAV counteracts HFD-induced obesity and improves insulin resistance,we could not conclude whether the effects come directly from its influence inadipose tissues or liver tissues." (PMID 35976267, 2022). "Indeed, for other cell types like the adipocytes, it was demonstrated that obesity affected adipocyte-released ELV content which exported a high proportion of obesity and IR-related proteins/lipids/RNAs from adipocytes able to modify the metabolic responses of other insulin-sensitive target cells." (PMID 34732797, 2021). "Thus, the differences in insulin signaling—at least in the DVC and PVN—may be associated with established obesity, rather than with the development of obesity." (PMID 35069259, 2021). "However, reduced sensitivity to insulin can also be observed in the absence of obesity." (PMID 33718425, 2021). "Interestingly, this IMCL accretion seems to be detrimental in obesity and T2D but not for endurance-trained athletes, who exhibit high oxidative capacity and enhanced insulin sensitivity despite their high levels of lipids within skeletal muscle, a process known as the “athlete paradox”." (PMID 33806797, 2021). "In conclusion, exercise training in women with obesity altered intramuscular phospholipid, cardiolipin, acylcarnitine, DAG and ceramide subtypes that were associated with content-driven changes in mitochondrial respiration, but not whole-body insulin sensitivity." (PMID 33770195, 2021). "Additionally, non-insulin-resistant children with overweight or obesity that changed to insulin-resistant during puberty showed a significant decrease in the concentration of 25(OH)D over time accompanied by a reduction in HDL concentrations and an increase in the TAG levels and WC." (PMID 34960039, 2021). "However, higher serum insulin levels were related to podocyturia, regardless of obesity." (PMID 34575240, 2021). "Levels of high molecular weight adiponectin, a hormone linked to insulin-sensitisation, were decreased in Phospho1−/− mice fed either a CD (2.62-fold) or a HFD (1.92-fold) (both p < 0.001) suggesting that insulin sensitivity and protection from obesity are independent of adiponectin." (PMID 33092598, 2020). "In a context of obesity, it should be clarified whether this is a positive effect that limits adipose tissue growth and therefore obesity development (or increase), or on the contrary, represents a negative effect for the maintenance of an adequate insulin function." (PMID 32784488, 2020). "Among others, increasing SAT basal and/or stimulated lipolysis during obesity elevates circulating free fatty acid (FFA) concentrations, which may interfere with glucose transport/uptake and phosphorylation activity, contributing to impaired peripheral insulin sensitivity." (PMID 32486525, 2020). "However, our prior work has already shown that extended morning fasting in an absence of exercise may impair insulin sensitivity and increase postprandial insulinemia in humans with obesity." (PMID 31628477, 2020). "Furthermore, mice in group HFD+B.theta showed no obesity and an insulin-resistant phenotype." (PMID 32019793, 2020).
Obesity (continued). "Taken together, these metabolic findings could suggest greater risk of glucose dysmetabolism and eventual T2D in SAM survivors, albeit in the current absence of overtly impaired insulin sensitivity or clinical disease that may develop with obesity and age based on oral glucose tolerance test (OGTT)." (PMID 33201860, 2020). "Thus, despite little differences in GTT and ITT, the fasting insulin levels of C57BL/6JRj on WD suggest an absence of hyperinsulinemia compared to C57BL/6JBomTac and C57BL/6J which complies with C57BL/6JRj being less susceptible to WD induced obesity." (PMID 32820201, 2020). "Therefore, our results indicate that obesity itself did not significantly contribute to striatal dysfunction in diabetic animals, and that hyperglycemia and decreased insulin‐dependent signaling are sufficient to generate dysfunctional dopamine neurotransmission." (PMID 32666590, 2020). "However, it is not clear whether reduced insulin clearance also contributes to hyperinsulinaemia independent of obesity." (PMID 31489455, 2019). "The effect of weight loss in lean patients with PCOS who are not overweight or obese in order to restore ovulatory function has not been studied sufficiently, which leaves an important question as to whether or not affecting insulin pathways in the absence of obesity will alleviate PCOS symptoms." (PMID 31367382, 2019). "Thus, the aim of this study was, using a mouse model, to determine the effects of obesity during pregnancy with and without an exercise intervention on maternal body weight and composition, nutrient handling and insulin and lipid signaling in liver, skeletal muscle, and adipose tissue." (PMID 31466137, 2019). "Thus upregulation or overexpression of SOCS protein in obesity in the liver, muscle and adipose tissue reduces the expression of IRS1 and 2 and their tyrosine phosphorylation induced by insulin, thereby leading to insulin resistance locally in the affected tissue and systemic insulin resistance." (PMID 31738794, 2019). "In this study, we tested whether HF diet affects BMAL1 function in an insulin-dependent manner by analyzing BMAL1 activity in the liver as well as in several extra-hepatic tissues under conditions of diet-induced obesity with or without application of the thiazolidinedione, rosiglitazone (ROSI)." (PMID 29795456, 2019). "However, alteration of brain insulin signaling may negatively impact on brain function also in the absence of T2D and before the onset of obesity." (PMID 31417349, 2019). "Furthermore, epidemiological studies do not address the ‘Obesity-Insulin-Testosterone’ connection." (PMID 31888528, 2019). "In addition, the TG, FBG, and insulin levels in the obesity subgroup were significantly higher than those in the normal weight subgroup, suggesting a positive correlation between body weight/BMI and TG, FBG, or insulin in olanzapine-treated schizophrenia patients." (PMID 31019532, 2019). "In addition, ATRAP activation therapy in insulin target organs (e.g., adipose tissue and skeletal muscle tissue) may be widely applied for treating lifestyle diseases that are not accompanied by obesity or hypertension." (PMID 29434287, 2018). "Use of BMI as a measure of obesity is limited as it does not account for lean/fat mass and other methods such as dual X-ray absorptiometry would have been preferable since percentage body fat is more closely related to both vitamin D levels and insulin resistance." (PMID 29692809, 2018). "It has been suggested that IL-15 and aberrant leptin secretion with obesity might instigate an adipose-specific NK-cell expansion and activation in response to high-fat diet overfeeding, stimulating NK-cell IFN-γ, TNF-α, and MCP-1 production, negatively impacting whole-body insulin sensitivity." (PMID 29479350, 2018).
Obesity (continued). "This cohort was matched for BMI and comprised insulin- sensitive and insulin-resistant subjects based on responses during a hyperinsulinaemic-euglycaemic clamp, meaning that we could identity pathways related to insulin sensitivity independent of obesity/BMI." (PMID 29402381, 2018). "Furthermore, childhood obesity is associated with a clustering of risk factors, such as elevated blood pressure, triglycerides, (reduced) HDL-C and LDL-C, and insulin, independent of the definition used for obesity and the methods used for central body fat deposition in children and adolescents." (PMID 29626333, 2018). "The main mechanistic pathways that involve obesity are systemic inflammation and the insulin-IGF-glucose axis, and the pathways that do not directly involve obesity may include oxidative stress, compromised DNA repair, altered gut microbiome, and diminished immune function." (PMID 30740588, 2018). "Furthermore, A. melanocarpa extract markedly inhibited the development of obesity and hyperlipidemia in HFD-induced obese mice, and A. melanocarpa extract treatment induced body weight changes were accompanied by improved glucose tolerance and insulin sensitivity in these obese mice." (PMID 30424495, 2018). "In addition, because all macronutrients have a role in insulin regulation, the proposed revision of the obesity concept may also have the advantage of not pointing to a single food and thus blaming a single item." (PMID 28485680, 2017). "The difference in the results may, therefore, be attributed to different subjects (subjects without known acute or chronic disease except for obesity in Haridas’ study vs. patients with T2D in ours) and duration of insulin exposure (3–6 hours in Haridas’ study vs. 3 month in ours)." (PMID 28717133, 2017). "Since the obesity and adiposity were less prominent in the Chinese and Asian populations than the Western populations, further large-scale longitudinal and interventional studies may be needed to elucidate the exact relationship between SDB and insulin resistance." (PMID 28081171, 2017). "In addition to alteration in insulin sensitivity that was independent of obesity, these studies have demonstrated more marked hyperandrogenemia, IR and relative hyperglycemia and lower sex hormone binding globulin (SHBG) in the obese compared with lean women with PCOS24." (PMID 28706269, 2017). "Obesity and T2DM are associated with increased plasma leptin levels, which fail to correct hyperglycemia in these patients because of the presence of leptin resistance, and these elevated plasma leptin levels are associated with IR, independent of obesity and insulin sensitivity." (PMID 28587203, 2017). "Even in the absence of obesity, this rat model already presented the main features of prediabetes, with fasting normoglycemia but reduced glucose tolerance, postprandial hyperglycemia, compensatory hyperinsulinemia, as well as decreased insulin sensitivity (resistance) and hypertriglyceridemia." (PMID 28635632, 2017). "Furthermore, serum levels of insulin and IGF-1 which increased in obesity and/or metabolic disease patients may be facilitate tumorigenesis, proliferation, survival and appear to be a major mechanism linking obesity to cancer." (PMID 28373897, 2017). "Crtc1 KO mice were significantly more glucose intolerant and insulin resistant than their wild-type littermates, suggesting that Crtc1 KO mice may have intrinsic, not necessarily obesity-dependent, defects in their peripheral tissue functions to maintain systemic metabolic homeostasis." (PMID 27869139, 2016). "However, after 30 min, no changes were noted for growth hormone, insulin, and insulin-like growth factor-1, suggesting that vibration may not be an effective method for obesity treatment." (PMID 27508150, 2016).
Obesity (continued). "Thus, impaired insulin action appeared not to be predictive for development of hepatosteatosis, beta cell mass regulation at the age > 6 months and ultimately also life span under conditions of obesity (F.K. manuscript in preparation)." (PMID 26540285, 2015). "In addition to the lack of consensus on the effect MnTBAP on insulin action, it remains unclear whether MnTBAP reduces adiposity in mice with pre-existing obesity." (PMID 26397111, 2015). "In addition, ALCAT1 was up-regulated by oxidative stress and diet-induced obesity, which indicated that ALCAT1 synthesized CL species with PUFA that were highly sensitive to oxidative damage, leading to mitochondrial dysfunction, reactive oxygen species production, and insulin resistance." (PMID 25415055, 2014). "Thus, the co-existence of obesity might accelerate myocardial lipid accumulation due to increased endogenous fatty acids and insulin supply, at least in women without disturbed glucose metabolism." (PMID 24621572, 2014). "The dissociation of adiponectin from the clusters related to parameters of insulin sensitivity in subcluster analyses of obesity subgroups (with or without T2D) maybe due to smaller group size and could be influenced by anti-diabetic medications or other factors." (PMID 24968098, 2014). "However, even if obesity promotes the decline of circulating vitamin D levels, excess weight is a common condition in diabetic patients and this does not exclude a possible interference of vitamin D on insulin secretion and action." (PMID 24747593, 2014). "Therefore, we analyzed the blood variables that help to define obesity, including the levels of lipids (nonesterified fatty acids, cholesterol, high- and low-density lipoprotein cholesterol, and triglycerides), glucose, and insulin." (PMID 25479564, 2014). "Indeed, this study clearly demonstrated that, although TSP1 deficiency does not prevent the development of high fat diet induced obesity, those animals displayed reduced inflammatory response and improved glucose and insulin homeostasis as compared to obese wild type mice." (PMID 24086512, 2013). "The findings that ATM that accumulates during obesity results in IR and that MCP-1mediates the recruitment of macrophages in tissues prompted us to further investigate the association of the increased insulin sensitivity observed upon OVX in the absence of MCP-1 with decreased ATM." (PMID 23977220, 2013). "The results suggest that hyperphagia and obesity, disorders of the primarily central origin, observed in IRS2-KO mice and neuron-specific IRS2-KO mice, could be, at least partly, due to impaired ability of NG neuron to sense insulin and thereby convey its information to the brain in IRS2-KO mice." (PMID 23840624, 2013). "However, the initial proinflammatory state created in early obesity may induce the accumulation of MDSC in an attempt to curtail overt inflammation, as described in other well-described models of inflammation, and may improve insulin sensitivity." (PMID 24455420, 2013). "In obesity, the activation of the c-Jun N-terminal kinase (JNK) and nuclear factor κ B (NF-κ B) transduction signals is key in the inflammation process of adipose tissue and these pathways could interact with insulin signaling via serine/threonine inhibitory phosphorylation of IRS." (PMID 24106481, 2013). "However, once the body weight reaches the obesity stage, further insulin secretion does not occur." (PMID 24137224, 2013). "Recent evidences suggest that these compounds also protect against obesity and co-morbities; their anti-adipogenic and anti-lipogenic effects may be due to the ability of estrogen receptors to interact with PPAR, thus modulating adipose development, insulin sensitivity and fatty acid metabolism." (PMID 23698776, 2013).
Obesity (continued). "To test this hypothesis, we investigated fasting blood glucose, insulin levels, the quantitative insulin-sensitivity check index (QUICKI) as an index of insulin sensitivity after 6-weeks of DHEA administration, exercise training, or both in rats with diet-induced obesity." (PMID 22647230, 2012). "Therefore, mice were fed cHF diet between 3 and 7 months of age to induce obesity and to impair glucose homeostasis, and then fed either cHF diet, or subjected to cHF+F, or cHF+PIO, or cHF+F+PIO treatment for 2 weeks, until performing an insulin tolerance test." (PMID 22073272, 2011). "Unexpectedly, the degree of obesity induced bythe post-weaning P diet was not exacerbated in offspring born to obese dams andplasma parameters were similar in both groups of leptin-resistant rats, excepthigher insulin and HOMA values and lower cholesterol level, in the PP than in the PCgroup." (PMID 21464991, 2011). "In addition, the significant association between lower E2 DNA copy numbers and lower level of postprandial 2hr insulin was evident only in non-diabetic women, whereas some obesity-related phenotypes and total cholesterol level exhibited significant associations only in non-diabetic men." (PMID 20624279, 2010). "Obese MASLD adolescents also exhibited significantly higher BMI, WC, TGs, LDL, insulin, HOMA-IR, and AST/ALT levels compared to non-obese MASLD and controls, underscoring the metabolic burden of obesity." (PMID 39910885, 2025). "The main risk factors for macrosomia include maternal age, pre-pregnancy obesity, excessive weight gain before and during pregnancy, and GDM without insulin use." (PMID 39940917, 2025). "In obesity, adipocyte CREB drives insulin resistance and transgenic mice expressing dominant‐negative CREB show increased insulin sensitivity." (PMID 39609264, 2025). "Significant differences in weight, BMI, HbA1c, fasting insulin, FBG, HOMA-B, total cholesterol, LDL-C, and non-HDL-C concentrations were observed between the obesity and nonobesity groups (p < 0.05)." (PMID 40843316, 2025). "Intravenous administration of DNase I significantly enhances insulin sensitivity in the PCOS model, independent of obesity." (PMID 40305335, 2025). "While these results clearly demonstrate a critical role of FFAR4 in the protective effects on obesity and CMDs, other studies showed that FFAR4 is not needed for the anti-inflammatory and insulin-sensitizing effects of n-3 PUFAs." (PMID 40427589, 2025). "The mechanisms by which obesity promotes CRC are multifactorial and not fully elucidated yet, but known to involve chronic inflammation, insulin resistance, neoangiogenesis, and alterations in adipokine levels." (PMID 40806335, 2025). "BMI, insulin, HOMA-IR, and TG levels were significantly higher in the obesity group compared to the without obesity group." (PMID 40806129, 2025). "Sevelamer improves insulin sensitivity and LDL-C in subjects with obesity, but these effects are independent of changes in circulating LPS." (PMID 40666326, 2025). "This interaction suggests that VDD may specifically potentiate obesity-related OSA mechanisms rather than acting as an independent risk factor, with implications including the role of vitamin D in adipose tissue inflammation, metabolic dysfunction, and insulin resistance." (PMID 41311801, 2025). "In the diet induced obesity (DIO) model of T2D, Gpt2βKO mice maintained lower non-fasting glucose and improved oral glucose tolerance and insulin secretion." (PMID 40630539, 2025). "Semaglutide efficiency in BWR was evaluated in both doses of 1 mg (approved for T2DM) and 2.4 mg (approved for obesity) in a STEP-2 trial, and 68.8% of subjects achieved a BWR ≥ 5% from the V0M, but insulin was notably not used in patients." (PMID 41007868, 2025). "Mean differences in serum maternal lipid and insulin concentrations, HOMA‐IR and HbA1c (%) in women with and without obesity during pregnancy." (PMID 40078195, 2025).